IDH2 (isocitrate dehydrogenase (NADP(+)) 2)
Diseases named in the same sentence as IDH2 in open-access papers (continued):
Sharing a sentence is not in itself a finding about the gene and the disease.
osteosarcoma (5 papers, 2013 to 2025). A usually aggressive malignant bone-forming mesenchymal neoplasm, predominantly affecting adolescents and young adults. "In the present study, the authors detected for the first time the mutation IDH2 R172K, which opens a window of questions regarding the events that connect IDH2 mutations and osteosarcoma development." (PMID 40288045, 2025). "For this study, we analyzed IDH1 and IDH2 mutations using 12 osteosarcoma specimens with direct DNA sequencing." (PMID 24403254, 2013). "All three cases included the IDH2-R172S mutant sequence (OS10, 14/16 (87.5%); OS11, 2/17 (11.8%); and OS12, 6/17 (35.3%)), demonstrating that all three osteosarcoma samples include IDH2-R172S mutations." (PMID 24403254, 2013). "This article describes the IDH2-R172S mutation in 3 of 12 (25%) osteosarcoma patients, which was detected by direct DNA sequencing." (PMID 24403254, 2013). "Herein, we newly report the IDH2-R172S mutation in three of 12 (25%) osteosarcoma patients, which was detected by direct DNA sequencing." (PMID 24403254, 2013). "Furthermore, the authors present, for the first time, the detection of the IDH2 R172K mutation in the plasma of an osteosarcoma patient, a result that should be further studied in a larger patient cohort." (PMID 40288045, 2025). "Interestingly, while some studies have investigated IDH1/2 mutations in osteosarcoma, only one study reported the novel detection of the IDH2 R172S mutation in three out of 12 osteosarcoma patients (25 %) using direct DNA sequencing." (PMID 40288045, 2025). "•Study highlights the detection of a novel IDH2 mutation in osteosarcoma." (PMID 40288045, 2025). "Unexpectedly, we found that MsMab-1 detected IDH2-R172S, which was discovered in 25% of osteosarcoma patients in this study." (PMID 24403254, 2013). "In contrast, three of 12 (25%) osteosarcoma samples, two of which were osteoblastic osteosarcoma (OB) and one of which was high-grade surface osteosarcoma (HGS), possessed IDH2 mutations." (PMID 24403254, 2013). "We next performed immunohistochemistry of MsMab-1 against IDH2-R172S-positive osteosarcomas because MsMab-1 strongly recognized IDH2-R172S proteins expressed in mammalian cells." (PMID 24403254, 2013). "MsMab-1 stained tumor cells of IDH2-R172S-positive osteosarcoma OS10 and OS11." (PMID 24403254, 2013). "Furthermore, MsMab-1 stained IDH2-R172S-expressing osteosarcoma tissues in immunohistochemistry." (PMID 24403254, 2013). "In that report, osteosarcoma samples from 222 patients, 19 osteosarcoma cell lines, and one chordoma cell line were tested for IDH1 mutations using the high-throughput MassARRAY platform: 64.4% (143 samples) of these were also analyzed for IDH2 mutations, including all chondroblastic osteosarcomas." (PMID 24403254, 2013). "The discrepancy between our detection of IDH2 mutations in osteosarcomas and their analysis has not been resolved; it might be dependent on ethnic differences." (PMID 24403254, 2013). "Furthermore, MsMab-1 detected IDH2-R172S expressed in U-2 OS human osteosarcoma cells, indicating that MsMab-1 is expected to be useful for immunohistochemical detection of IDH2-R172S osteosarcomas." (PMID 24403254, 2013). "Although IDH2-WT and IDH2-R172S were transfected into U-2 OS osteosarcoma cell line, no morphological or growth difference was observed among those cells 2 days after transfection." (PMID 24403254, 2013). "Although we found IDH2-R172S of osteosarcomas in this study, no inhibitor against IDH2-R172S has been discovered." (PMID 24403254, 2013).
Alpha-thalassemia (4 papers, 2019 to 2023). Alpha-thalassemia is an inherited hemoglobinopathy characterized by impaired synthesis of alpha-globin chains leading to a variable clinical picture depending on the number of affected alleles.
breast tumors (4 papers, 2016 to 2025). "In this study, through the analysis of large-throughput biological data of breast tumors, combined with the characteristics of the biological process of ferroptosis, the specific gene IDH2 was found to be significantly highly expressed in TNBC and functionally correlated with ferroptosis." (PMID 38413708, 2024). "Notably, PHGDH inhibitors effectively suppress the growth of IDH2-overexpressing breast tumors in pre-clinical models, indicating that targeting PHGDH could be a promising approach for TNBC with IDH2 overexpression." (PMID 39973065, 2025). "CCR7, EZR, IDH2 and MMP9 were highly expressed in breast tumor tissues, whereas they were expressed at low levels in normal breast tissues (p < 0.001)." (PMID 38438469, 2024). "The results showed that CCL5 and IDH2 were not significantly differentially methylated in BRCA, while CCR7, EZR, IL8, and IL2RG were hypermethylated in normal tissues, and FLT3, MAPK10, and MMP9 were hypermethylated in breast tumor tissues." (PMID 38438469, 2024).
erythroleukemia (4 papers, 2016 to 2020). Acute erythroid leukemia characterised by the presence of at least 50% erythroid precursors and at least 20% myeloblasts in the bone marrow. "The first IDH2 inhibitor developed was AGI-6780, which induced thex differentiation of IDH2 mutated erythroleukemia and primary human AML cells." (PMID 33182517, 2020). "In a haematological model (erythroleukemia), IDH2 mutation caused methylation changes, which were successfully reversed by its inhibitor; similarly, it impaired the EPO-induced differentiation, which was restored upon mutant IDH2 inhibition." (PMID 27145078, 2016). "Recent studies revealed that allosteric inhibitors could selectively inhibit IDH2/R140Q and induce differentiation of TF-1 erythroleukemia and primary human AML cells." (PMID 29184081, 2017). "In addition, inhibition of mutant IDH2 by a selective IDH2/R140Q inhibitor induces differentiation of an erythroleukemia cell line and primary human AML cells." (PMID 27577048, 2016).
Hepatic steatosis (4 papers, 2018 to 2022). Steatosis is a term used to denote lipid accumulation within hepatocytes. "Thus, we hypothesized that the BAT from the IDH2 mice might prevent the HFD-induced body weight gain and the associated metabolic consequences, including hepatic steatosis." (PMID 32015410, 2020).
liver cancer (4 papers, 2018 to 2023). An epithelial or non-epithelial malignant neoplasm that arises from the liver. "There is a growing body of evidence of the use of metabolomics for diagnosis and therapy of liver cancers, especially with metabolites of TCA cycle, miRNA, IDH1 and IDH2." (PMID 36768732, 2023). "IDH2 and SLC25A1 in liver cancer were found to have a positive Spearman correlation (R = 0.20, P = 1.931e-4)." (PMID 37741815, 2023).
lymphoid neoplasm (4 papers, 2021 to 2023). A neoplasm composed of a lymphocytic cell population which is usually malignant (clonal) by molecular genetic and/or immunophenotypic analysis. "There is also a major difference in the distribution of IDH2 mutations which are very common in haematopoietic and lymphoid tumours but rare in all other tumour types." (PMID 33740099, 2021). "Mutations of the R140 in IDH2 are virtually exclusive to haematopoietic and lymphoid tumours." (PMID 33740099, 2021). "The IDH2 R140Q detected in our cohort is known to transform cells in vitro and induces myeloid and lymphoid neoplasms in mice." (PMID 34058070, 2021).
Myocardial fibrosis (4 papers, 2024 to 2025). "Quercetin was also found to promote desuccinylation of isocitrate dehydrogenase (IDH2) via SIRT5, maintain mitochondrial homeostasis, and alleviate myocardial fibrosis, ultimately reducing the risk of HF." (PMID 41178953, 2025). "Quercetin protects mouse cardiomyocytes against inflammation, ameliorates myocardial fibrosis, and reduces the incidence of HF by activating SIRT5, which promotes IDH2 desuccinylation and maintains mitochondrial homeostasis." (PMID 41260100, 2025).
pilocytic astrocytoma (4 papers, 2017 to 2025). Pilocytic astrocytoma is a rare subtype of low-grade glioma of the central nervous system characterized by a well circumscribed, often cystic, brain tumor with a discrete mural nodule and long, hair-like projections that extend from the neoplastic astrocytes. "Furthermore, IDH1 or IDH2 mutations have not been identified in any pilocytic astrocytomas (WHO grade I), indicating a different tumorigenic mechanism." (PMID 40103938, 2025).
triple-negative breast carcinoma (4 papers, 2024 to 2025). An invasive breast carcinoma which is negative for expression of estrogen receptor (ER), progesterone receptor (PR), and human epidermal growth factor receptor 2 (HER2). "Similarly, IDH2 is significantly overexpressed in triple-negative breast cancer (TNBC) and is associated with an unfavorable prognosis." (PMID 41212437, 2025). "Here we show that wild-type IDH2 is highly expressed in triple negative breast cancer (TNBC) cells and promotes their proliferation in vitro and tumor growth in vivo." (PMID 38658533, 2024). "Here, the authors show in preclinical murine models that wild-type IDH2 is a potential therapeutic target for triple-negative breast cancer." (PMID 38658533, 2024). "The first publication identifies wild-type IDH2 as a crucial factor in the survival of triple-negative breast cancer (TNBC) cells, with its inhibition leading to disrupted energy metabolism, reduced tumor growth, and enhanced apoptosis." (PMID 39409901, 2024). "Our study revealed that the LINC00571/HNRNPK/ILF2/IDH2 axis promoted the progression of triple-negative breast cancer by regulating tricarboxylic acid cycle metabolites." (PMID 38238853, 2024). "In triple-negative breast cancer (TNBC), wild-type IDH2 has been identified as a crucial driver of tumor survival and proliferation, with its inhibition leading to impaired energy metabolism, reduced tumor growth, and enhanced apoptosis." (PMID 39409901, 2024). "In triple-negative breast cancer (TNBC), it was found that wild-type IDH2 is essential for tumor survival, as its inhibition leads to disrupted energy metabolism and reduced tumor growth." (PMID 39409901, 2024).
anaplastic oligodendroglioma (3 papers, 2018 to 2021). A WHO grade III oligodendroglioma with focal or diffuse malignant morphologic features (prominent nuclear pleomorphism, mitoses, and increased cellularity). "The mutation of IDH1 or IDH2 genes is observed in all anaplastic oligodendrogliomas with 1p/19q codeletion, and this mutation concerns the IDH1 gene in the present case study." (PMID 31248444, 2019).
biliary tract cancer (3 papers, 2020 to 2023). "When we explored cBioPortal for IDH1/2 mutations in biliary tract cancers (n = 182), including gallbladder cancer, IDH1 and IDH2 mutations were found to be restricted to codon 132 and codon 172, respectively." (PMID 32978444, 2020). "In this review article, we will focus on the IDH1/IDH2 pathway, discussing the preclinical rationale of its targeting as well as the promises and challenges of the clinical development of IDH inhibitors in biliary tract cancers." (PMID 33182517, 2020).
bladder cancer (3 papers, 2018 to 2025). "In bladder cancer, the acquired mutation of isocitrate dehydrogenase 2 (IDH2) can induce reductive glutamine metabolism, stabilize the expression of HIF-1α, thus stimulate aerobic glycolysis and pentose phosphate pathway (PPP), and promote gemcitabine resistance." (PMID 41281744, 2025).
brain cancer (3 papers, 2017 to 2022). A primary or metastatic malignant neoplasm affecting the brain. "Importantly, the loss of 5-hmC in brain cancer did not exhibit any correlation with IDH1 or IDH2 mutations." (PMID 29290954, 2017).
cervical carcinoma (3 papers, 2019 to 2021). A carcinoma arising from either the exocervical squamous epithelium or the endocervical glandular epithelium. "In conclusion, hypoxia induced OIP5-AS1 promotes the Warburg effect through miR-124-5p/IDH2/HIF-1α pathway in cervical cancer." (PMID 34513821, 2021). "All in all, the results in the present study suggest that hypoxia induced OIP5-AS1 promotes the Warburg effect through miR-124-5p/IDH2/HIF-1α pathway in cervical cancer." (PMID 34513821, 2021). "Taken together, OIP5-AS1 promotes IDH2 by inhibiting miR-124-5p in cervical cancer cells." (PMID 34513821, 2021). "Similarly, dual fluorescent gene reporting system and western blot analysis shows miR-124-5p targeted inhibition of IDH2 expression in cervical cancer cells in normoxic and hypoxic condition." (PMID 34513821, 2021). "In cervical cancer cells, OIP5-AS1 promotes IDH2 expression by inhibiting miR-124-5p, and IDH2 promotes the Warburg effect of cervical under hypoxic condition through regulating HIF-1α expression." (PMID 34513821, 2021). "To investigate the mechanism of OIP5-AS1 in the regulation of Warburg effect in cervical cancer, we analyzed the sequence in online database, and found that miR-124-5p as a bridge connecting OIP5-AS1 and IDH2." (PMID 34513821, 2021). "Taken together, the present study indicates that the high expression of OIP5-AS1 promoted the Warburg effect through miR-124-5p/IDH2/HIF-1α pathway in cervical cancer, and is a potential cervical cancer treatment target." (PMID 34513821, 2021). "We found that Fra-1 overexpression restored mitochondrial function in cervical cancer cells via the SIRT3 signaling pathway, and Fra-1 increased the expression of IDH2 and SOD2." (PMID 33102485, 2020). "The results indicated that Fra-1 up-regulated the expression of SIRT3, which led to changes in IDH2 and SOD2 expression as downstream molecules, and finally reduced the ROS content in cervical cancer cells." (PMID 33102485, 2020). "Therefore, we examined the effect of Fra-1 overexpression on SIRT3, IDH2, and SOD2 expression in cervical cancer cells." (PMID 33102485, 2020).
heart failure (3 papers, 2020 to 2024). Inability of the heart to pump blood at an adequate rate to meet tissue metabolic requirements. "Inactivated IDH2 by HNE (4-hydroxy-2-nonenal) addiction was observed at the early hypertrophy stage of heart failure." (PMID 39594567, 2024). "Since IDH2 also produces NADPH for GSH/GSSG and the thioredoxin system to maintain redox homeostasis within the mitochondria, impaired IDH2 activity therefore was suggested as an early mitochondrial oxidative stress marker in heart failure." (PMID 39594567, 2024). "Consistent with the role of IDH2 in regulating cardiac mitochondrial NADPH, a previous study showed that IDH2KO mice developed accelerated heart failure with impaired mitochondrial function, and were more susceptible to pathologic hypertrophy in a pressure-overload model." (PMID 32015410, 2020).
hemangioma (3 papers, 2021 to 2025). A benign vascular lesion characterized by the formation of capillary-sized or cavernous vascular channels. "Mutations in the IDH2 gene have been identified in D2HGA2 patients exhibiting angiokeratomas and hemangiomas." (PMID 39839460, 2025).
Multiple Myeloma (3 papers, 2019 to 2024). "Previous studies have demonstrated that in multiple myeloma, IDH2 enhances the expression of WNT7B and activates the WNT signaling pathway by targeting the m6A demethylase FTO, thereby promoting the occurrence and development of multiple myeloma." (PMID 39641872, 2024).
muscular dystrophy (3 papers, 2019 to 2022). Muscular dystrophy (MD) refers to a group of more than 30 genetic diseases characterized by progressive weakness and degeneration of the skeletal muscles that control movement. "The expression of mutated IDH2 has been associated with white matter abnormalities throughout the central nervous system (CNS) and with muscular dystrophy in transgenic adult mice." (PMID 30921354, 2019). "Global expression of mutant IDH2 in transgenic mice-induced dilated cardiomyopathy and muscular dystrophy." (PMID 32948843, 2021).
Myelodysplasia (3 papers, 2021 to 2026). Clonal hematopoietic stem cell disorders characterized by dysplasia (ineffective production) in one or more hematopoietic cell lineages, leading to anemia and cytopenia.
myeloid leukemia (3 papers, 2015 to 2024). A clonal proliferation of myeloid cells and their precursors in the bone marrow, peripheral blood, and spleen. "First, shRNA was used to specifically knock down IDH2 expression in two myeloid leukemia lines (U937 and ML-1) that harbor wild-type IDH2 gene and then examined the impact of decreased IDH2 expression on AML cells survival and proliferation." (PMID 35313945, 2022).
neuroblastoma (3 papers, 2015 to 2024). Neuroblastoma (NB) is the most common solid, extracranial childhood tumor. "In agreement with our results, previous studies have reported that enhanced c-Myc and N-Myc expression makes neuroblastoma and B-cells addicted to glutamine and suppression of glutamine metabolism, by inhibition of IDH1, IDH2 or GLS expression reduces cellular proliferation and tumor growth." (PMID 28430666, 2017).
skull base tumors (3 papers, 2022 to 2025). "A phase II clinical trial evaluating the use of enasidenib in IDH2-mutated malignant sinonasal and skull base tumors, including olfactory neuroblastoma, was recently initiated, and the results will be relevant to cases like the one reported here." (PMID 40062188, 2025).
squamous cell carcinoma (3 papers, 2017 to 2022). A carcinoma arising from squamous epithelial cells. "The level of IDH2 was also higher in serum from patients with lung adenocarcinoma and squamous cell carcinoma compared with healthy control subjects, but was similar between the two histologic patient groups." (PMID 29465809, 2018). "While normal tissue, squamous cell carcinomas and cases from the ACC tumor class were mostly assigned to distinct groups, the differentiation between olfactory neuroblastomas, cases from the NEC-like IDH2 and NEC-like SMARCA4/ARID1A class was less evident." (PMID 36443295, 2022). "With regards to routine histopathological workup, we identified KRT18 in combination with UCHL1 as potential immunohistochemical markers to differentiate NEC-like IDH2 and NEC-like SMARCA4/ARID1A tumors from adenoid cystic carcinomas, olfactory neuroblastomas and squamous cell carcinomas." (PMID 36443295, 2022). "UCHL1 expression was high in NEC-like IDH2 and NEC-like SMARCA4/ARID1A tumors as well as olfactory neuroblastomas but absent in tumors from the ACC class and squamous cell carcinomas." (PMID 36443295, 2022).